BCL2 (BCL2 apoptosis regulator)
Diseases named in the same sentence as BCL2 in open-access papers (continued):
Sharing a sentence is not in itself a finding about the gene and the disease.
tumor (continued). "Treatment with IL30 also upregulated tumor progression genes, such as Ar (3.27 times), Bcl2 (3.25 times), IL6 (3.90 times), Cav2 (7.60 times), Ndrg3 (4.5 times), Sept7 (4.10 times) and Sfrp1 (7.46 times)." (PMID 36224639, 2022). "As testified by WB results, overexpressing RFX3-AS1 up-regulated Vimentin, N-cadherin, and Bcl2 while down-regulated E-cadherin, Bax, and c-Caspase3 in the formed tumor tissues (P < 0.05)." (PMID 35475457, 2022). "Compared to shRNA control group, BCL-2 expression was significantly increased in the tumor tissues from shRNA AGK group, and AS1842856 treatment abolished the enhanced expression of BCL-2." (PMID 35910796, 2022). "In animal experiments, we confirmed that the changes in the expression levels of PUMA, Bax, Bcl-2, p21, Cyclin D1 and P-p65 in tumor tissues were consistent with those observed in vitro." (PMID 35759135, 2022). "The decrease in cell proliferation marker Ki67 and anti-apoptotic protein Bcl-2 also indicated the inhibition of tumor growth by circRTN4 knockdown." (PMID 34983537, 2022). "MiRNA-15/16 is another family of tumor suppressing miRNA that regulates Bcl-2 levels and has reduced expression in various cancer." (PMID 35056993, 2022). "A research on human epithelial cancer cells thought that the KOR promoted apoptosis of tumor cells via the PKC or Bcl-2 pathway." (PMID 35966857, 2022). "Remarkably, the co-delivered ABT199 can specifically bind to the Bcl-2 proteins to inhibit the activation of Bcl-2 and facilitate the tumor cell apoptosis in vitro and in vivo." (PMID 36297356, 2022). "Protein levels of MS4A10, MS4A8, MS4A7, PCNA, BAX, Bcl-2, Caspase-3, and cleaved Caspase-3 were measured in tumor tissues." (PMID 36438804, 2022). "A series of functional assays illustrated BCL-2-mediated apoptosis in the tumor cells as a potent anti-cancerous mechanism." (PMID 36358660, 2022). "Like in other cancers, in CRC, the Bcl-2 proteins, which facilitate apoptosis, are dysregulated and contribute to tumor growth, progression, and therapy resistance." (PMID 36430867, 2022). "Consistently, BCL2 expression of pretreatment samples was negatively correlated with the degree of tumor regression and progression-free survival (PFS)." (PMID 36202798, 2022). "Herein, we have investigated the regulatory role of BCL-2 in T cells in the CLL tumor microenvironment." (PMID 35193595, 2022). "In this context, Bcl-2 inhibition represents one more challenge towards reprogramming resistant neoplasms to undergo drug-induced apoptosis." (PMID 35631543, 2022). "While treatment with the Bcl-2 inhibitor Navitoclax results in the reduction of metastases in tumor bearing mice, treatment with the Mcl-1 inhibitor S63845 leads to complete elimination of senescent tumor cells and metastases." (PMID 35449130, 2022). "Curcumin is another natural compound which mediates its anti-tumor effects by increasing the ratio of BAX to Bcl-2, leading to increased rates of apoptosis." (PMID 35884592, 2022). "Previous studies have proven that a decrease in the ratio of Bcl-2/Bax induces a positive effect/significance for tumor treatment." (PMID 35807546, 2022). "There was a decrease in the expression of ENAH, Bcl-2, Bcl-x, N-cadherin, and Snail in tumor tissues of the group treated with hUC-MSC-EV transfected with miR-375 compared to control animals." (PMID 35955703, 2022). "The tumor itself is resistant to Fas-mediated lysis by activated lymphocytes presumably because tumor cells overexpress BCL2 in the cytoplasm." (PMID 35517798, 2022).
tumor (continued). "CD57 and MSA was expressed in 12 cases (80%); ten of 15 tumors (67%) had different positivity for Bcl2 in 2%–100% of tumor cells." (PMID 36699621, 2022). "Treatment with this disaccharide induces antineoplastic impacts toward EAC, as demonstrated by a significant decrease in tumor volume, body weight, number of viable tumor cells and the BCL2 expression as the anti-apoptotic gene." (PMID 36497321, 2022). "Since the expression of Bcl-2 protein in tumor cells is much higher than that in normal cells, inhibitors targeting it have little effect on normal cells." (PMID 36313628, 2022). "Eventually, VTX induces the release of proapoptotic from Bcl-2 and restores apoptosis in tumor cells." (PMID 35682939, 2022). "Bcl2 expression showed significant relationships with histological grading (P<0.001), tumor extent (P=0.003), nodal metastasis (P=0.004), pathological stage (P<0.001), and the presence of lymphovascular invasion (P<0.001)." (PMID 36532636, 2022). "The combination of these two elements decreased Bcl-2 expression and mitochondrial membrane potential (ΔΨm) while inhibiting tumor growth of HCC xenografts." (PMID 36230494, 2022). "NCL also bound to the 3’ UTR of Bcl-2 mRNA, increasing its stability and allowing tumor cells to escape the apoptotic pathway." (PMID 35861882, 2022). "Overexpression of Bcl2 in tumor-specific T cells promoted cell survival and therapeutic efficacy of adoptively transferred T cells infiltrating mouse melanomas." (PMID 35573704, 2022). "Activation of Bcl-2 can increase the cancer stem cell-like behavior of Hep3B, promoting cell growth and tumor metastasis." (PMID 35308206, 2022). "Meanwhile, high Bcl-2 expression has been reported to inhibit the sensitivity of tumor cells to therapeutic drugs." (PMID 36297356, 2022). "Cancer cells escape apoptosis by the upregulating of anti-apoptotic Bcl2 proteins (Bcl2, Bcl-XL and Mcl1), and this upregulation significantly adds to tumor progression, poor prognosis, and chemo resistance." (PMID 36267274, 2022). "The inhibition of Bcl2 sensitized tumor cells to IL-24, a cytokine known to exert an antitumor effect." (PMID 36685574, 2022). "For OS, CD3 positivity was an independent favorable prognostic factor, and Ki-67 positivity>0%, tumor size <2 cm, multifocal lesions, BCL-2 and C-MYC coexpression, and deep brain involvement were independent adverse prognostic factors." (PMID 35875161, 2022). "Downregulation of Mcl-1 upon mTOR inhibition was accompanied by a reduction in tumor volume, which was further reduced upon co-treatment with the Bcl-2/Bcl-xL inhibitor ABT-263." (PMID 35053443, 2022). "Bax was slightly increased in the tumor lysates of clone #92, and the ratio of Bcl2/Bax was three times higher in the tumor lysates of the vector control clone #V1 than that of clone #92." (PMID 36362174, 2022). "Another promising Bcl-2 inhibitor gossypol showed anti-tumor effects on temozolomide-resistant GBM tumorspheres." (PMID 36309485, 2022). "After adjusting for multiple clinical variables (IPI, cell of origin, BCL2 status, and total metabolic tumor volume), all four scales retained significant prognostic value (all p < 0.05) for OS." (PMID 35322932, 2022). "The results of this study in vivo and in vitro show that the overexpression of BNIP3 can promote the proliferation of DLBCL cells, promote tumor growth, and inhibit cell apoptosis, increase the level of Bcl-2, and reduce Bax." (PMID 35783530, 2022). "For instance, the anti-apoptotic protein Bcl-2 is overexpressed in OC, and treatment of tumor cells with a combination of cisplatin or carboplatin and Bcl-2 inhibitors show an increased level of cancer cell death induction." (PMID 35743145, 2022).
tumor (continued). "In the context of the clinical trial, the authors were unable to confirm the in vivo delivery of the miRNAs to the tumor site or to detect changes in Bcl-2 and CCND1 expression." (PMID 35205318, 2022). "We detected the effects of AGS-Q and AGS-H on Bax, Bcl-2 and cleaved-Caspase-3 proteins in tumor tissue." (PMID 35445056, 2022). "It was reported that STAT3 can induce abnormal proliferation of tumor cells through regulation of BCL-2, FAS, survivin and CyclinD1." (PMID 35513871, 2022). "By extracting tumor tissue proteins and conducting Western blotting experiments, the Bcl-2 protein increased and Bim protein levels decreased in tumor tissues with overexpressed SNORD89 (*P < 0.05)." (PMID 35790714, 2022). "Not only immune cells but also senolytic drugs such as BCL-2 inhibitors can selectively eliminate senescent cells and, thus, blunt the potentially tumor growth-promoting SASP." (PMID 35563820, 2022). "A feature of tumor cells is that they avoid the processes of initiating cell death by upregulating members of the Bcl-2 anti-apoptotic family, such as Bcl-2, and decreasing the expression of pro-apoptotic genes, as well as Bax and Bad." (PMID 35050083, 2022). "Multiple studies have suggested that decreased Bcl-2/Bax ratio in tumor cells triggers activation of caspase-9/-3 and subsequently promotes the mitochondrial-mediated apoptosis." (PMID 36387351, 2022). "Expression levels of ZEB1, YAP1, CCND1, and BCL2 were consistent with the database analysis and demonstrated significantly high values in tumor tissues (logFC ≥ 1.5)." (PMID 35453574, 2022). "Thymax pretreatment revealed more marked upregulation in tumor cells for Bax expression by 4.3 fold and caspase-3 by 3.4 fold, while the expression of Bcl-2 was downregulated by 67.9% versus Inocul Control mice." (PMID 35299600, 2022). "Cisplatin-resistant tumor is characterized by apoptosis resistance and high expression of various anti-apoptotic/pro-survival proteins such as Bcl-2 and survivin." (PMID 35264959, 2022). "HepG2-derived exosomes loaded with G3139, which is an ASO targeting the anti-apoptotic protein Bcl-2, were efficiently delivered to tumor cells and observed to downregulate Bcl-2 in vitro." (PMID 35054611, 2022). "Anti-apoptotic protein Bcl-2 has a protective role in tumor cells by promoting tumor cell growth and proliferation and inhibiting apoptosis." (PMID 34980181, 2022). "Rare examples of hypomethylation leading to activation of genes that are important in cancer have resulted in the overexpression of Bcl-2 and R-ras, resulting in the inhibition of apoptosis of tumor cells." (PMID 36009359, 2022). "Tumor cells promote the upregulation of non-BCL-2 antiapoptotic proteins through numerous other biological processes." (PMID 36313732, 2022). "Consistently, treatment with OPE resulted in an increase in the expression ratio of Bax/Bcl2 in tumor tissues." (PMID 35504024, 2022). "The tumor size measurements indicated britanin treatment inhibited tumor growth by upregulating the expression of Bax and downregulating the expression of Bcl-2, and suppressing NF-κB activation, which is related to a decrease in nuclear p65 levels." (PMID 36296934, 2022). "When Bcl-2 is overexpressed, this leads to tumor formation, as in CLL and follicular lymphoma, inappropriate cell survival, and chemotherapy resistance." (PMID 35682939, 2022). "Some siRNAs, such as Bcl-2 siRNA, can target the Bcl-2 gene, inhibit Bcl-2 protein synthesis, and induce apoptosis of tumor cells." (PMID 35335138, 2022).
tumor (continued). "With regard to NSCLC pathogenesis, increased expression of the anti-apoptotic protein Bcl-2 and reduced levels of the pro-apoptotic protein Bax have been reported to be correlated with chemoresistance and tumour development." (PMID 35379783, 2022). "OPE promoted apoptosis of tumor cell in the mouse model Cleaved caspase 3 expression and Bax/Bcl2 ratio were also enhanced." (PMID 35504024, 2022). "ABT-199 has a strong inhibitory effect on Bcl-2 and can promote the apoptosis of tumour cells with high Bcl-2 expression." (PMID 36386146, 2022). "Venetoclax is an approved chemotherapy drug for CLL, which inhibits BCL-2 expression in tumor cells as well as in immune T lymphocytes." (PMID 35193595, 2022). "This resulted in an increase in the Bax/Bcl-2 ratio and high production of the pro-apoptotic protein caspase-3 within tumor cells." (PMID 36080252, 2022). "Bcl-2 can regulate tumor cell apoptosis and inhibit cancer cell proliferation through the mitochondrial pathway." (PMID 35991644, 2022). "Meanwhile, the Bcl-2 gene increases the number of tumor cells and leads to the further development and proliferation of tumors by inhibiting apoptosis." (PMID 36618947, 2022). "Both miR-15a and miR-16-1 target apoptosis regulator Bcl2 (BCL2) to promote cell death, acting as tumor suppressors." (PMID 35966635, 2022). "For example, USP11 stabilizes eIF4B, which acts as a transcription factor to increase the mRNA translation of tumor proteins such as cMYC, BCL2, and BCL6, thereby promoting oncogenic translation." (PMID 35359344, 2022). "Of note, we also found that NOX4 expression positively correlated with HIF1α (resistant marker), Glut1 and LDHA (glycolytic markers), and Ki67; whereas it negatively correlated with Bcl2 in tumor tissues in patients with PTC." (PMID 35396551, 2022). "In the miR-383/Bcl-2 pathway, decreased miR-383 expression together with elevated Bcl-2 expression was found in GC tissues compared to normal control specimens, which was related to advanced tumor stages and higher metastasis." (PMID 36313570, 2022). "In the analysis for PFS, all four scales had prognostic value after adjusting for IPI alone; only physical functioning was prognostic after adjusting for IPI and other variables (cell of origin, BCL2 status, and total metabolic tumor volume)." (PMID 35322932, 2022). "By targeting, Bcl2, an antiapoptotic gene, and Sirt1, the ectopic expression of miR-34a inhibited the proliferation of tumor cells and induced apoptosis." (PMID 36685574, 2022). "HA-PEG-nHA-ZOL NP-induced upregulation of BAX, Bcl-2, and caspase 3 destroyed the tumor metabolism balance and triggered the tumor apoptosis." (PMID 35694235, 2022). "Mcl-1 is upregulated in senescent tumor cells, including cells expressing low levels of Bcl-2, an established target for senolytic therapy." (PMID 35449130, 2022). "Nuciferine suppressed tumor weight and size by downregulating the expression of various proteins, such as Ki-67, Bcl-2, CDC2, HIF-1α, and N-cadherin." (PMID 35158798, 2022). "Both, proapoptotic BCL-2 or MAP kinase pathway members (BIK, BAK1, MAP3K12, and MAPK9) and proliferation-associated tumor drivers (FOS, HOXA3, and POLR2B) had an increased gene expression." (PMID 35778418, 2022).
tumor (continued). "Several marine peptides can change the Bcl-2/Bax ratio, activate caspases, and release Cyt C to induce cell apoptosis by stimulating Ca2+ overload and ROS production in tumor cells." (PMID 35200639, 2022). "PARK2 also regulates the activity of several apoptosis-related proteins of the Bcl-2 family, including Bax, Bcl-2, and Mcl1, promoting apoptosis of tumor cells." (PMID 35847032, 2022). "Bcl-2/Bax signaling pathway is one of the classic apoptosis signals, which mediate apoptosis of many tumor cells." (PMID 36686743, 2022). "An important superfamily of antiapoptotic proteins known as the B-cell lymphoma (Bcl-2) appear to be upregulated in LC, promoting cytotoxic resistance through the dysregulation of apoptosis in tumor cells." (PMID 35163777, 2022). "Meanwhile, in vivo experiments have demonstrated that usnic acid is significantly more effective in inhibiting tumor growth without affecting body weight and in regulating the amount of Bax and Bcl2 in tumor tissues than 5-FU alone." (PMID 36364296, 2022). "Taken together, our data demonstrate specific sensitivities of patient-derived GSC to individual BH3-mimetics and increased expression of anti-apoptotic BCL-2 proteins in both primary GBM tumour tissues and GSCs." (PMID 35473984, 2022). "The binding of venetoclax to the BH-3 domain of BCL-2 leads to the displacement of the pro-apoptotic protein BIM from BCL-2, and the subsequent activation of cytochrome c-mediated intrinsic apoptosis in tumor cells shows a high expression of this protein." (PMID 35326111, 2022). "In CRC, the JAK/STAT3 pathway can directly regulate tumor immune cells and upregulates the expression of oncogenic proteins, such as c-MYC, Cyclin D1, BCL2 or MCL1 to help drive tumor progression and chemoresistance." (PMID 35501324, 2022). "Combined use of XPO1 and BCL2 inhibitors can synergistically induce the apoptosis of DHL tumor cells in vitro, and most importantly, block tumor progression and spread in vivo." (PMID 35303910, 2022). "When MCF-7 cells were treated with OEO, the expressions of genes related to apoptosis (BIM and Bcl-2), tumor suppression (PTEN), and cell growth inhibition (AURKA), were evaluated using real-time PCR." (PMID 36678556, 2022). "For example, the overexpression of Bcl-2 can inhibit chemotherapy or radiotherapy-induced tumor cell apoptosis." (PMID 35869506, 2022). "An example of a mechanism that tumor cells use to prevent apoptosis is to increase the expression of the anti-apoptotic protein (Bcl-2) and decrease the expression of the pro-apoptotic protein genes (Bax and Bad)." (PMID 35050083, 2022). "Combining BH3 mimetics has also emerged as a promising strategy to target BCL-2 protein-mediated resistance and enhance tumour cell killing, with early in vitro studies showing that MCL-1 knockdown overcomes ABT-737 resistance." (PMID 35568716, 2022). "Another study indicated an increase in Bax protein expression while a decrease in Bcl-2 protein expression, which further proved the promoting effect of stigmasterol on apoptosis of tumor cells." (PMID 36578938, 2022). "A decrease in tumor growth and downregulation of Smad3, N-cadherin, and Bax expression and significant upregulation of E-cadherin and Bcl-2 expression were observed after administering the exosomes." (PMID 35955703, 2022). "Several favorable outcomes such as suppression of cell proliferation, increase in cell apoptosis and caspase-3 expression, and decrease in Bcl-2 and tumor xenograft growth (in vivo) were observed." (PMID 36230494, 2022). "In tumor advancement, proto-oncogenes such as c-Myc and Bcl-2 are considered as genes that regulate cellular proliferation and apoptosis." (PMID 35890188, 2022).